HPRT1 (hypoxanthine phosphoribosyltransferase 1)
Diseases named in the same sentence as HPRT1 in open-access papers (continued):
Sharing a sentence is not in itself a finding about the gene and the disease.
tumor (continued). "Three genes, HSPB1, HPRT1, and GFPT1, were found to be significantly upregulated in tumor samples compared to normal samples." (PMID 38875364, 2024). "We pinpointed 8 human-derived genes (PHF14, PELP1, RPL7L1, HPRT1, RELN, RNU1-75P, RNU5A-8P, RNVU1-19), likely to represent tumor-specific signals as a signature combining these genes demonstrated high accuracy in assessing therapy response." (PMID 39337470, 2024). "In this study, we found that HPRT1 was overexpressed in EGFR-mutant LUAD cells and tissues, and HPRT1 promoted cell proliferation in vitro and tumor growth in vivo." (PMID 39343971, 2024). "To further evaluate the performance of the screen, we assessed the enrichment of gRNAs targeting well-characterised 6-TG sensitivity genes HPRT1 and NUDT5, as well as those in the mismatch repair pathway, in treated tumours." (PMID 37684549, 2023). "AFF4 depletion impaired tumor formation, and rescued simultaneous expression of HPRT1 and IMPDH2 recovered tumor formation and tumor growth." (PMID 37063434, 2023). "In tumor tissues, the staining intensity of the target genes was strong (BID, HPRT1, SMN1), high (PGAM5), or medium (FADD, KIAA1191)." (PMID 37760507, 2023). "IHC also determined that the expression of HPRT1 and MMP1 were consistent in the tumor tissues of nude mice." (PMID 35205603, 2022). "Taking our findings together, we recommend HPRT1 and PPIA as the best reference genes for relative quantification in gene expression studies comparing normal and tumor endometrial tissues." (PMID 25473950, 2014). "In normality test, ACTB, HPRT1, and 18S rRNA in 'normal stomach tissues' group and all genes except for GAPDH in 'tumor stomach tissues' followed normal distribution by KS-test." (PMID 20507635, 2010). "HPRT1 also promotes EMT and tumor proliferation through STAT3 interaction." (PMID 40699765, 2025). "HPRT1 plays an important role in the recycling of nutrient-scarce purines in the hypoxic TME, while the role of TYMP in pyrimidine metabolism and angiogenesis suggests its contribution to tumour proliferation." (PMID 39457550, 2024). "HPRT1 deficiency reduced tumor growth even without IACS-010759 treatment, but compared to the control tumors, HPRT1-deficient tumors were more sensitive to IACS-010759." (PMID 38876105, 2024). "Our study revealed that in most cancer types, HPRT1 expression did not significantly vary by sex, age, tumor stage, or status." (PMID 38159260, 2024). "Importantly, we revealed that the TMZ metabolite AICA is a bona fide substrate of HPRT1 and is converted to the AMPK activator AICAR for tumor cell survival under TMZ treatment." (PMID 37737247, 2023). "This indicates that HPRT1 and PGK1 may have a grade dependency, and could serve as biomarkers for tumor aggressiveness." (PMID 30679932, 2019). "The results of our analysis proved that the expression of reference genes in our cohort of patients, including only endometrioid histotype and carefully selected and balanced according to their tumor grade, was dependent on tumor grade for B2M, GAPDH, H3F3A, GUSB, HPRT1, POLR2A and UBC." (PMID 25473950, 2014). "Significant expression increase from normal to tumor stomach tissues (p < 0.05) were observed in HPRT1 (p = 0.011) and 18S rRNA (p = 0.021), but not in ACTB (p = 0.058), GAPDH (p = 0.918), B2M (p = 0.740), or RPL29 (p = 0.208)." (PMID 20507635, 2010). "HPRT1, B2M, and RPL29 in tumor stomach tissues passed the normality in DAP- and SW-tests." (PMID 20507635, 2010). "As anticipated, hypoxic conditions did not change the level of GAPDH or HPRT-1 in the tumor cells, which served as internal controls (results not shown)." (PMID 19696929, 2009). "In this study we assessed the RNA quality of 738 tumour samples before pre-amplification and evaluated the pre-amplification success by measuring the expression of two low abundant reference genes (SDHA and HPRT1)." (PMID 19930725, 2009).
tumor (continued). "PPIA showed |ΔCt| = 1.45 ± 0.17, and GAPDH and HPRT1 had the highest difference in |ΔCt| (on average) between normal and tumor samples: 2.42 ± 0.20 for GAPDH and 1.91 ± 0.21 for HPRT1." (PMID 19014639, 2008). "Furthermore, the findings suggested that HPRT1 and PYGL might play critical roles in reshaping the tumor microenvironment." (PMID 37371537, 2023). "Besides, we observed no significant changes in the HPRT1 mRNA expression levels in the tumor tissues of patients with HNSCC of different ages in both cohorts." (PMID 34231338, 2021). "Although RPL29-HPRT1 combination has been suggested as the best for 'all stomach tissues' by geNorm, it is also evident that HPRT1 expression has increased from normal to tumor and this combination is not considered suitable one." (PMID 20507635, 2010). "In contrast, knocking out hypoxanthine phosphoribosyltransferase 1 (HPRT1), a crucial enzyme involved in the purine salvage pathway, had no impact on tumor cell proliferation, indicating the specific dependence of HB cells on DNPS for cell proliferation." (PMID 40097378, 2025). "The lack of normal groups for CESC, OV, UCEC, and UCS, as well as the absence of tumor groups for PRAD and TGCT in the sex-based differential expression study of HPRT1, precluded analysis of these cancers." (PMID 38159260, 2024). "Tumour and non-tumour tissues in all 20 tissues analysed expressed similar levels ofYBX1,GAPDH,HPRT1,ZFAS1, andAGAP2-AS1 RNAs." (PMID 33447385, 2020). "These four genes were consequently excluded from geNorm analysis and the three candidate controls whose expression levels did not significantly vary between normal and tumor tissues (HMBS, HPRT1 and TBP) were reevaluated by the geNorm software." (PMID 19257903, 2009). "Moreover, HPRT1 and CARNS1 expression levels were negatively correlated in clinical tumor samples, whereas no such correlation was observed in 2D‐cultured cell lines." (PMID 41365579, 2025). "Furthermore, IHC was performed using an antibody against Ki67 and we observed that simultaneous expression of HPRT1 and IMPDH2 promoted tumor growth from cells lacking AFF4, proving a genetic axis of AFF4/HPRT1& IMPDH2 is existed in PDAC cells." (PMID 37063434, 2023). "RQ by RPL29 (T/N = 2.23×, p = 0.071), HPRT1 (T/N = 1.34×, p = 0.258), ACTB (T/N = 1.60×, p = 0.395), 18S rRNA (T/N = 1.36×, p = 0.527) and RPL29-HPRT1 (T/N = 1.76×, p = 0.086) also showed increasing GPNMB expression in tumor stomach tissues but it was not statistically significant." (PMID 20507635, 2010).
cancer (74 papers, 2007 to 2025). A tumor composed of atypical neoplastic, often pleomorphic cells that invade other tissues. "In the current study, these two immune checkpoint-blocking therapeutic biomarkers were significantly associated with HPRT1 in many cancers." (PMID 38159260, 2024). "HPRT1 was expressed at higher levels in endometrial cancer than in normal tissue and was significantly associated with cancer grade." (PMID 38159260, 2024). "HPRT1 expression is associated with the occurrence and progression of multiple cancer types, such as BRCA, HNSC, LUAD, LUSC, PRAD, and UCEC." (PMID 38159260, 2024). "HPRT1 was also found to be associated with drug resistance in cancer cells and has been proposed as a therapeutic target of chemotherapeutic drugs." (PMID 35205603, 2022). "HPRT1 was also found to be associated with drug resistance, such as cisplatin, in cancer cells and has been proposed as a therapeutic target of chemotherapeutic drugs." (PMID 35844514, 2022). "Hypoxanthine phosphoribosyl transferase 1 (HPRT1) is traditionally believed to be a housekeeping gene; however, recent reports suggest that it is upregulated in several cancers and is associated with clinical outcomes." (PMID 32532008, 2020). "The expression of HPRT1 has been implicated in the immune microenvironment of several cancers, although its role in different cancers may be mediated by affecting different immune cells." (PMID 38159260, 2024). "HPRT1 expression is associated with the immune microenvironment of certain cancers, and its role in various cancers may be by affecting various immune cells." (PMID 38159260, 2024). "mRNA expression of cancer-associated genes and genes involved in extracellular matrix regulation were measured using quantitative real time PCR relative to the expression of the housekeeping gene HPRT1 from the same patient." (PMID 35160252, 2022). "However, recent reports have indicated that HPRT1 overexpression is associated with a poor prognosis in various types of cancers." (PMID 35205603, 2022). "Increased expression of HPRT1 was observed in many cancer types, indicating that HPRT1 may be a potential diagnostic and prognostic marker." (PMID 35127477, 2021). "Moreover, HPRT1 and its associated genes were observed to be enriched for several cancer‐related pathways, including DNA replication and cell cycle." (PMID 34231338, 2021). "Compared with normal controls, HPRT1 RNA levels in breast cancer tissues were significantly elevated, particularly in basal cells and triple-negative breast cancer, suggesting its involvement in cancer progression by positively regulating genes associated with cancer pathways." (PMID 38159260, 2024). "This study highlights the importance of 3D culture systems for elucidating context‐dependent metabolic regulation and evaluating therapeutic targets in cancer, using HPRT1‐KO cells with a dysfunctional purine salvage pathway as a model." (PMID 41365579, 2025). "Correlation heatmaps revealed that in most pan-cancer tumors, HPRT1 expression positively correlated with immunoinhibitors, immunostimulators, and MHC molecules." (PMID 38159260, 2024). "HPRT1 has significant prognostic significance in some cancers, suggesting its potential value in cancer treatment and prediction." (PMID 38159260, 2024). "This study highlights the multifaceted role of HPRT1 in a variety of cancer types, which provides a theoretical basis for its potential as a novel therapeutic strategy." (PMID 38159260, 2024). "Based on the TCGA data, HPRT1 was differentially expressed in 19 cancer tissues compared to corresponding normal tissues." (PMID 38159260, 2024). "The results suggested that, in 17 cancer types, the mortality risks were significantly elevated in the individuals in the group with high HPRT1 expression in comparison to those with low HPRT1 expression." (PMID 38485739, 2024). "By controlling adenosine production, HPRT1 upregulation is able to suppress the immune microenvironment of malignant tumors." (PMID 38159260, 2024).
cancer (continued). "First, there were significant differences in HPRT1 expression and activity across multiple cancers compared to paired normal tissues." (PMID 38159260, 2024). "Using data from the The Cancer Genome Atlas (TCGA) database, the HPRT1 expression profile and its potential for predicting prognosis was assessed in different cancer types." (PMID 38485739, 2024). "HPRT1 was reported to play a critical role in cancer progression and chemoresistance, including HNSCC." (PMID 37371537, 2023). "HPRT1 is recognized as a significant contributor to cancer progression and chemoresistance, particularly in HNSCC." (PMID 37371537, 2023). "The expression of HPRT1 in different cancers was significantly higher than that of the corresponding control tissues." (PMID 35205603, 2022). "We applied the GEPIA2 approach to analyze the expression status of HPRT1 across various cancer types of TCGA." (PMID 35205603, 2022). "HPRT1 has traditionally been used as a housekeeping gene; however, many recent studies have found a potential relationship with various types of cancer." (PMID 35205603, 2022). "First, we applied the TIMER2 approach to analyze the expression status of HPRT1 in various types of cancer of TCGA." (PMID 35205603, 2022). "The results showed that the HPRT1 mRNA expression was significantly up‐regulated in cancer tissues compared with healthy control samples, which was consistent with the findings of our quantitative real‐time PCR analysis for 45 paired HNSCC and normal tissues." (PMID 34231338, 2021). "The unusual genetic interaction network of HPRT1, as seen in both proteomics and RNA, makes this region of the network a rich hunting ground for mechanisms of cancer progression." (PMID 34007962, 2021). "To confirm the role of these two enzymes in controlling cancer cell proliferation, we conducted gene knockout (KO) assays and found that the simultaneous deletion of HPRT1 and NT5E markedly reduced A549 cell proliferation." (PMID 34703880, 2021). "Hypoxanthine phosphoribosyltransferase (HPRT1), as a salvage pathway enzyme, plays a crucial role in modulating the cell cycle and has been reported to be overexpressed in multiple cancers." (PMID 34231338, 2021). "The results have suggested that patients with cancer with high expression of the HPRT1 gene probably were sensitive to tozasertib, teniposide, manumycin A, clofarabine, GSK‐J4, COL‐3, CD‐437, BRD‐K01737880 and 3‐Cl‐AHPC and resistant to abiraterone." (PMID 34231338, 2021). "Of note, HPRT1 was found to be highly expressed in testis when compared to other normal tissue types in a manner similar to many cancer/testis genes (CT genes)." (PMID 32532008, 2020). "The expression of HPRT1 was computed in fragments per kilobase of million mapped reads (FPKM) for individual cancer types as well as aggregated across all cancer types from The Cancer Genome Atlas (TCGA)." (PMID 32532008, 2020). "Altogether, these results suggest that HPRT1 is a biomarker with prognostic value in a majority of cancer types." (PMID 32532008, 2020). "Collectively, our results essentially highlight the importance of and change the way in which HPRT1’s function is studied in biology, warranting careful examination of its role in cancer." (PMID 32532008, 2020). "Further, HPRT1’s role in nucleotide recycling, which is critical in providing the building blocks for the uncontrolled proliferation of cancer cells, indicates its function in cancer." (PMID 32532008, 2020). "Upon further evaluation, we also found HPRT1 expression to be higher in other carcinomas and adenocarcinomas and observed that higher HPRT1 expression is closely associated with poorer clinical outcomes." (PMID 32532008, 2020). "To test PASTMUS strategy in mapping functional elements of proteins, we selected three genes (ANTXR1, CSPG4, and HBEGF) encoding bacterial toxin receptors and three genes (HPRT1, PLK1, and PSMB5) encoding cancer drug targets." (PMID 31842968, 2019).
cancer (continued). "There is an upregulation of HPRT1 in certain cancer types, making it a promising biomarker for the treatment of these cancers." (PMID 30031396, 2018). "In contrast, GPER mRNA normalized to GADPH or HPRT1 mRNA was higher in benign and borderline tumours than in malignant tumours." (PMID 24001041, 2013). "HPRT1 was recommended as a universal, single reference gene for differential expression studies in cancer research." (PMID 19200351, 2009). "-Elevated expression of HPRT1 in malignant tissues of several types of cancers." (PMID 40717738, 2025). "Therefore, HGprt can be used as a surface antigen for targeted immunotherapies, and HPRT1 can be used as a biomarker for the detection and treatment of cancer." (PMID 40717738, 2025). "We used the CellMinerTM database to study a potential correlation analysis between drug sensitivity and HPRT1 expression in pan-cancer, and the results showed that HPRT1 expression was positively correlated with drug sensitivity to chelerythrine, fenretinide, ifosfamide, and obatoclax." (PMID 38159260, 2024). "In this study, the expression, clinical prognostic value, and potential mechanisms of HPRT1 in various cancers were preliminarily explored, revealing that this gene exists as a carcinogenic gene in various tumors and is closely related to the immune microenvironment of tumors." (PMID 38159260, 2024). "Collectively, these data imply that HPRT1 may promote cancer progression by inhibiting YAP protein phosphorylation in the downstream Hippo signaling pathway." (PMID 38485739, 2024). "We first investigated the role of HPRT1 in pan-cancer prognosis using the Cox model." (PMID 38159260, 2024). "TMB correlation analysis showed that HPRT1 expression was correlated with TMB of most cancers." (PMID 38159260, 2024). "HPRT1 emerges as a promising biomarker for predicting and treating diverse cancer types." (PMID 38159260, 2024). "However, increasing evidence has indicated the differential expression of HPRT1 and its urgent role in cancer cells due to the increased demand for nucleotide synthesis and consequently HPRT1 during the cell cycle." (PMID 35205603, 2022). "The expression level of HPRT1 increased across many cancer types." (PMID 35586208, 2022). "HPRT1 is highly expressed in many common cancers and corresponds to a poor clinical prognosis." (PMID 35205603, 2022). "The HPRT1 aberrant expression has been documented in several cancers." (PMID 34231338, 2021). "Some researchers have suggested that the HPRT1 gene, as a crucial component of the purine salvage pathway, plays a role in mediating the proliferation, autophagy and apoptosis‐related processes in cancer cells." (PMID 34231338, 2021). "HPRT1’s increased expression level across several cancer types suggest that HPRT1 could act as a potential prognostic marker." (PMID 32532008, 2020). "Interestingly, tumor suppressor gene CDH1 was upregulated upon HPRT1 knockdown, reiterating HPRT1’s role in cancer biology." (PMID 32532008, 2020). "HPRT1 is considered a housekeeping gene and is widely used as an endogenous control in gene expression studies; however, recent studies, including our data, have revealed its potential involvement in cancer." (PMID 32532008, 2020). "Additionally, higher HPRT1 expression predicts poorer overall survival in a variety of cancer patients, which signifies its clinical value." (PMID 32532008, 2020). "The prognostic value of HPRT1 in other cancer types was evaluated using a pan-cancer database." (PMID 32532008, 2020). "We found that HPRT1 that was traditionally thought to be a housekeeping gene may actually have a role in cancer biology." (PMID 32532008, 2020). "Moreover HPRT1 has previously been recommended as a universal reference gene for differential expression studies in cancer research." (PMID 25473950, 2014).